NLRP3 (NLR family pyrin domain containing 3)
Diseases named in the same sentence as NLRP3 in open-access papers (continued):
Sharing a sentence is not in itself a finding about the gene and the disease.
steatosis (continued). "NLRP3 and mature IL1β levels were also elevated in the livers of patients with steatosis and NASH compared with livers from healthy controls." (PMID 37739179, 2023). "In HFD-fed mice, PFOS facilitates liver inflammation and steatosis through the activation of NLRP3 (NLR family pyrin domain containing 3) inflammasome that mediates hepatocyte pyroptosis." (PMID 37242221, 2023). "Taken together, our results suggest that ATL I acts as a promising compound that activates SIRT6/PPARα signaling and attenuates the NLRP3 inflammasome to ameliorate hepatic inflammation and steatosis." (PMID 36558977, 2022). "These protective effects are mainly mediated through lipid metabolism, NLRP3 inflammasome, and steatosis." (PMID 35004731, 2021). "Firstly, the palmitate acid-induced hepatocytes steatosis involved the activation of NLRP3 inflammasome and increased secretion of IL-1β and IL-18." (PMID 32477116, 2020). "Our results support this, as the group of Nlrp3−/− mice under HFD presented reduced levels of steatosis compared to WT mice." (PMID 31998283, 2019). "FTZ suppressed this NLRP3 inflammasome activation to prevent steatosis, hepatic inflammation, and fibrogenic phenotype changed." (PMID 30140364, 2018). "The involvement of NLRP3 inflammasome in ALD has been demonstrated by a robust expression of NLRP3, caspase-1 and IL-1β in alcohol-fed mice, while liver inflammation and steatosis are dramatically attenuated in NLRP3−/− or caspase-1−/− mice." (PMID 30319645, 2018). "This inhibitory effects of FTZ on NLRP3 inflammasome activation reduced both hepatic inflammation and steatosis." (PMID 30140364, 2018). "In contrast, the Nlrc4−/− mice had the lowest NAFLD activity scoring for steatosis after ethanol feeding compared to B6 and Nlrp3−/− mice." (PMID 24453428, 2013). "Histological analysis for steatosis in liver sections from each strain indicated that Nlrp3−/− mice had greater NAFLD activity scoring for steatosis in the pair-fed animals yet had a similar score as B6 when fed Lieber DeCarli ethanol-containing diet." (PMID 24453428, 2013). "For example, cyanidin-3-O-glucoside has been shown to reduce oxidative stress, inhibit NLRP3 activation, and alleviate steatosis in HFD-induced models by upregulating PINK1–Parkin expression and enhancing their mitochondrial localization, thereby promoting PINK1-mediated mitophagy." (PMID 41391771, 2025). "In conclusion, our research results show that BSP-1 can improve liver injury and steatosis caused by MASLD in both in vitro and in vivo experiments, this effect may be attributed to the regulation of the pyrother-related NLRP3/caspase-1/GSDMD pathway." (PMID 40626309, 2025). "Moreover, sUA stimulates the production of reactive oxygen species by activating NADPH oxidases, particularly NOX4, leading to aberrant activation of NLRP3, which contributes to hepatic steatosis and inflammation." (PMID 40089555, 2025). "In addition to fibrosis and hepatic stellate activation in the MetALD murine model, NLRP3 inflammasome activation was shown to contribute to steatosis and inflammation in MASLD and ALD, respectively." (PMID 38891092, 2024). "Our study demonstrates that the intercellular communication between monocytes, hepatocytes and neutrophils is orchestrated by the NLRP3-IL-1β axis and therapeutic inhibition of NLRP3 in the early phase of MetALD prevents liver damage, inflammation and steatosis." (PMID 38891092, 2024). "This study aimed to investigate the expression levels of NLRP3 inflammasome and IL-1β genes in the blood of patients with MAFLD with various degrees of fibrosis and steatosis to provide new insights into the possible role of the NLRP3 inflammasome pathway in the pathogenesis of MAFLD." (PMID 39179677, 2024).
steatosis (continued). "The same group also demonstrated that the NLRP3/caspase-1/IL-1β signaling axis acts as a key character in the progression of steatosis, the inflammatory response and cellular injury in ALD, and that inhibiting the IL-1 signaling pathway alleviated these symptoms." (PMID 37250902, 2023). "Moreover, the aberrant activation of the NLRP3 inflammasome is considered the main factor to drives immune outbreaks in relation to hepatic injury, inflammation, steatosis, and fibrosis." (PMID 36160411, 2022). "The diagnostic performance of serum NLRP3 was also high in discriminating significant steatosis (grade 0–1) from non-significant steatosis (grade 2–3) (AUC = 0.917, P < 0.001)." (PMID 36376416, 2022). "We also provided an alternative mechanism by which ATL I binds with SIRT6 to activate PPARα and its target genes and suppresses inflammatory factor release by attenuating NFκB-mediated NLRP3 inflammasome formation, which, together, attenuate hepatic inflammation and steatosis." (PMID 36558977, 2022). "Compared with the SBS group, the SBS+MFGM group showed lower liver pathology scores of steatosis and inflammation, less MPO positive cells and reduced expressions of NLRP3, apoptosis-associated speck-like protein containing a CARD (ASC), Caspase-1, interleukin (IL)-1β(P < 0.05) in the liver." (PMID 35308293, 2022). "However, we and others have demonstrated elsewhere that inhibition of AGEs production or blocking of AGE/RAGE signalling reverses both SREBP1c and NLRP3 upregulation, concomitantly improving steatosis and inflammation." (PMID 34462492, 2021). "The role of NLRP3 in the progression from steatosis to NASH has also been documented recently." (PMID 32472368, 2020). "Consumption of a HFD resulted in an abnormal appearance with atypical yellowish coloration of the livers from WT mice with severe steatosis and lipid droplet accumulation, while livers from Nlrp3−/− and Asc−/− (Pycard−/−) mice retained dark red coloration without steatosis." (PMID 31379826, 2019). "Indeed, numerous experimental observations suggest an involvement of NLRP3 in transition from steatosis to NASH." (PMID 29270247, 2017). "Therefore, BSP-1 plays a role in alleviating MASLD by preventing steatosis, inflammation, and pyroptosis, which may be relate to the inhibition of NLRP3/caspase-1/GSDMD signaling pathway." (PMID 40626309, 2025). "The activation of NLRP3 inflammasome followed by caspase-1 activation allows the release of proinflammatory cytokines, such as IL-1β and IL-18, into the extracellular space that promote inflammatory cell death (pyroptosis), leading to an increase in liver inflammation, steatosis, and fibrosis." (PMID 35563780, 2022). "Indeed, steatosis progression to steatohepatitis and fibrosis originates from the uncontrolled increase of oxidative damage and inflammatory cascade and then is sustained by the activation of NLRP3 inflammasome which promotes Casp1-dependent IL-1β production." (PMID 33265944, 2020). "In the present study, after characterization of roles in which NLRP3 inflammasomes play in NASH, we also examined whether FTZ prevents NASH development by targeting the effects of NLRP3 inflammasome activation on both inflammatory response and steatosis in the liver." (PMID 30140364, 2018). "In vivo administration of the NLRP3 inhibitor, MCC950, improves the early phase of MetALD by preventing liver damage, steatosis, inflammation, and immune cells recruitment." (PMID 38891092, 2024). "Animal experiments have shouwn upregulation of NLRP3, ASC, and Caspase-1 gene levels in the liver of NAFLD animals with steatosis." (PMID 38566171, 2024). "Liver cell damage progresses from simple steatosis to NASH to fibrosis, and each process is related to the NLRP3 inflammasome signaling pathway." (PMID 37250902, 2023).
steatosis (continued). "Moreover, it has been shown that the NLRP3 inflammasome plays an important role in steatosis, inflammation, and fibrosis in experimental models of liver disease and that blocking its activation could be a potential therapy to slow down the progression of the disease." (PMID 35563780, 2022). "Evidence supporting a crucial role of NLRP3 activation in ALD includes the marked protection of mice with global knockout of caspase-1, ASC, and IL-1β receptor which exhibit alleviated steatosis and inflammation." (PMID 35563780, 2022). "Inflammasome activation is also a common characteristic of NASH, and human livers with steatosis or NASH present decreased TFEB and increased p62/SQSTM1, LC3-II, and NLR family pyrin domain containing 3 (NLRP3) expression." (PMID 30249977, 2018). "Although there was an increase in the expression levels of NLRP3 in advanced steatosis, this increase was not statistically significant." (PMID 39179677, 2024). "Nlrp3−/− and Gsdmd−/− ALD mice showed an increased gut bacterial load, decreased ileal expression of E‐cadherin, more severe ileitis, pronounced liver damage, steatosis and higher plasma levels of FITC‐dextran, D‐LA and ZO‐1 compared with WT mice." (PMID 39605303, 2024). "Such crystals have been shown to distinguish between steatosis and NASH in humans and mice, coincide with increased cholesterol, and appear to nucleate at lipid droplets and stimulate NLR family pyrin domain containing 3 (NLRP3) inflammasome activity." (PMID 36712976, 2022). "In addition, HLF increased the activities of plasma SOD, CAT, and GSH-Px and decreased the levels of Casp 1, NLRP3, IL-1β, IL-18, and TNF-α, improving the degree of hepatocyte steatosis and inflammatory infiltration of rats." (PMID 36425260, 2022). "The absence of the NLRP3 inflammasome complex reduced, in both young and old mice, the degree of steatosis compared to WT controls, showing a lower globular deformation of hepatocytes and a lower degree of lobular inflammation." (PMID 32977490, 2020). "In fact, NLRP3−/− mice are protected by diet‐induced NASH, while human liver specimens of NASH subjects denoted increased gene expression of NLRP3 in comparison with those with steatosis only." (PMID 32314869, 2020). "We first determined whether NLRP3 inflammasome formation and activation occurred during the development of NASH using a mouse model of steatosis induced by HFD." (PMID 30140364, 2018). "Although the mRNA levels of NLRP3 inflammasome components were upregulated in the liver of early steatosis in animal models, the NLRP3 inflammasome was not shown activated." (PMID 29312290, 2017). "Based upon the reduced Nlrp3 and IL-1β mRNA expression in the livers of both the DIO and ob/ob clodronate-treated mice, we hypothesized that IL-1β might play a key role in steatosis development in hepatocytes." (PMID 25216251, 2014). "Our experiments with in vivo administration of the NLRP3 inhibitor, MCC950, show that the NLRP3 inhibition can block all of the early effects of a MASH diet and alcohol on the liver by preventing liver damage, steatosis, inflammation, neutrophil infiltration and NETs." (PMID 38891092, 2024). "As a consequence, hyperactivation of lipogenesis, which has been previously demonstrated to be directly activated by AGEs21,43, was enhanced, while the increased expression of Gal-3 contributed to both the persistent NLRP3 inflammasome activation, not depending on NFkB, and steatosis." (PMID 34462492, 2021). "In contrast, mice lacking TXNIP exhibit exacerbated steatosis and liver inflammation when fed an MCD diet, suggesting a negative regulatory role of TXNIP on NLRP3 and its protective role in MASH." (PMID 39917567, 2025). "Numerous studies have shown that pyroptosis is an inflammatory link between simple steatosis and NASH, since no NLRP3 activation was observed in simple steatosis without inflammation, while NLRP3 activation in NASH has been shown in both human and animal models." (PMID 34630100, 2021).
familial cold autoinflammatory syndrome (60 papers, 2007 to 2026). Familial cold urticaria (FCAS) is the mildest form of cryopyrin-associated periodic syndrome (CAPS) and is characterized by recurrent episodes of urticaria-like skin rash triggered by exposure to cold associated with low-grade fever, general malaise, eye redness and arthralgia/myalgia. "Caspase-1 inhibition prevents familial cold autoinflammatory syndrome-associated NLRP3 mutant-mediated inflammasome assembly." (PMID 35616535, 2022). "Pannexin 1 inhibition prevents familial cold autoinflammatory syndrome-associated NLRP3 mutant-mediated inflammasome assembly." (PMID 35616535, 2022). "Constitutive NLRP3 activation causes cryopyrin-associated periodic syndromes: familial cold autoinflammatory syndrome, Muckle–Wells syndrome, and neonatal-onset multisystem inflammatory disease." (PMID 35629398, 2022). "Mutations in the NLRP3 gene have been linked to several autoinflammatory disorders including Muckle–Wells syndrome, familial cold autoinflammatory syndrome, and chronic infantile neurologic cutaneous and articular syndrome." (PMID 26444566, 2015). "Notably, among these conditions, NLRP3-AID was initially recognized in 2001 as the underlying factor leading to familial cold autoinflammatory syndrome (FCAS)." (PMID 37854599, 2023). "Further, activating mutations in the NLRP3 gene mediate hereditary autoinflammatory diseases ranging in severity from the mild familial cold autoinflammatory syndrome (FCAS) to the severe neonatal-onset multisystem inflammatory disease (NOMID)." (PMID 32983094, 2020). "Additionally, gain-of-function mutations in the NLRP3 gene contribute to autoinflammatory diseases, including familial cold autoinflammatory syndrome (FCAS) and Muckle–Wells syndrome (MWS)." (PMID 36322773, 2022). "Interestingly, the study of patients with autosomal dominant cold-induced urticaria, later termed familial cold autoinflammatory syndrome (FCAS), allowed the identification of mutations in the CIAS1/cryopyrin/NLRP3 gene." (PMID 28588486, 2017). "The SNP (−1064 T) has been found in the NLRP3 gene of a mutation negative familial cold autoinflammatory syndrome (FCAS) patient." (PMID 32883606, 2020). "The NLRP3 gene was identified as the genetic locus for three dominantly inherited periodic fevers: familial cold autoinflammatory syndrome (FCAS), Muckle-Wells syndrome, and chronic infantile neurological cutaneous articular syndrome/neonatal onset multisystem inflammatory disease (CINCA/NOMID)." (PMID 29850543, 2018). "Germline mutations in NLRP3 and NLRP12 are associated with familial cold autoinflammatory syndrome." (PMID 19300480, 2009). "Neonatal-onset multisystem inflammatory disease (NOMID) is the most severe form of familial cold autoinflammatory syndrome (FCAS), caused by mutations in the CIAS1 gene encoding NLRP3 protein." (PMID 37275856, 2023). "NLRP3-AID comprises three distinct presentations with increasing severity: familial cold autoinflammatory syndrome (FCAS), Muckle–Wells syndrome (MWS), and neonatal-onset multisystem inflammatory disorder (NOMID), also known as chronic infantile neurological cutaneous articular syndrome (CINCA)." (PMID 38481988, 2024). "The cryopyrinopathies encompass a spectrum of disease states including, from mild to severe, familial cold autoinflammatory syndrome (FCAS), Muckle–Wells syndrome (MWS), and neonatal onset multisystem inflammatory disease (NOMID) caused by autosomal dominant or de novo mutations in the NLRP3 gene." (PMID 28178435, 2017).
familial cold autoinflammatory syndrome (continued). "At the same time, the advantage in accuracy is absolutely overwhelming for the genes GATA2, MEFV, and NLRP3, which relate with IMD21 (immunodeficiency 21, monocytopenia and mycobacterial infection syndrome), Familial mediterranean fever, and Familial cold autoinflammatory syndrome, respectively." (PMID 39975544, 2025).
myocarditis (60 papers, 2017 to 2026). Myocarditis is a condition that is characterized by inflammation of the heart muscle (myocardium). "Many of these anti-inflammatory effects are caused by the inhibition of the NLRP3 inflammasome in active immune cells during vascular and myocardial inflammation." (PMID 39969632, 2025). "In conclusion, these results suggest an association between mitochondrial ROS and NLRP3 inflammasome activation in CVB3-induced myocarditis." (PMID 35997820, 2022). "In a murine myocarditis model, colchicine abrogated myocardial inflammation, linked with splenic NLRP3 reduction." (PMID 32440911, 2021). "We report on an adolescent girl with arrhythmogenic biventricular cardiomyopathy and three acute myocarditis-like episodes in whom we found a novel truncating DSP variant accompanied by a known low penetrance R490K variant in the NLRP3." (PMID 33207704, 2020). "IL-1β was elevated in our cohort of patients, and together with upstream NLRP3 inflammasome activation and associated cytokines may play a role in the pathogenesis of myocarditis." (PMID 37146127, 2023). "NLRP3 inflammasome is strongly associated with CVB3‐induced myocarditis." (PMID 32508013, 2020). "Moreover, in the NLRP3 knockout mice study, NLRP3 knockout was more associated with significantly increased virus loads, although chronic and excess inflammatory responses constitute vital contributors in the development of myocarditis." (PMID 35997820, 2022). "It is a good choice to inhibit the activation of NLRP3 inflammasome and downstream inflammatory pathways to improve cardiac function of myocarditis rats." (PMID 40642003, 2025). "In mice with LPS-induced cardiomyopathy, sodium tanshinone IIA sulfonate mitigates myocardial inflammation and enhances cardiac function by promoting autophagy and inhibiting NLRP3 inflammasome activation, leading to increased survival rates." (PMID 39925805, 2025). "The occurrence and progression of myocarditis is inseparable from the mediation and participation of NLRP3 inflammasome." (PMID 40642003, 2025). "Supporting this, interventions like IL-1 blockade or NLRP3 inhibition ameliorate experimental myocarditis." (PMID 40832143, 2025). "Post-infarction myocardial inflammation was characterized by increased Asc and Nlrp3 gene expression and caspase-1, IL-1β, and Nlrc4 protein expression." (PMID 40332346, 2025). "In fructose-induced myocarditis, cinnamaldehyde also improves cardiac function by regulating NLRP3 expression." (PMID 40146271, 2025). "In myocarditis, NLRP3 expression increases as part of the immune response; we observed higher NLRP3 levels in the experimental and treatment groups than in the control group." (PMID 38650023, 2024). "Because these dysregulations were mitigated in the treatment group, we believe that MCC950 can be used to target NLRP3 to mitigate myocarditis-induced abnormalities in Ca2+ signaling." (PMID 38650023, 2024). "Treatment of the experimental rats with anti-NLRP3 antibodies blocked the myocarditis-induced activation of Ca2+ signaling, implicating NLRP3 in the dysregulation of Ca2+ signaling in myocarditis." (PMID 38650023, 2024). "Rats with myosin peptide–induced myocarditis (experimental group) were treated with an NLRP3 inhibitor (MCC950; 10 mg/kg, daily for 14 days) or left untreated." (PMID 38650023, 2024). "Further research is needed to explore the potential therapeutic implications of targeting the NLRP3 inflammasome in human myocarditis." (PMID 39075540, 2024). "Myocarditis increased the infiltration of inflammatory cells into cardiac tissue and upregulated the expression of NLRP3; these observations were more prominent in the RVOT and RVA than in the LV." (PMID 38650023, 2024). "Therefore, in patients with myocarditis, NLRP3 signaling may be targeted to reduce the risk of VA." (PMID 38650023, 2024). "This suggests a direct correlation between NLRP3 activity and arrhythmogenic events in rats with myocarditis." (PMID 38650023, 2024).